BIRC3 (baculoviral IAP repeat containing 3)
Description:
Multi-functional protein which regulates not only caspases and apoptosis, but also modulates inflammatory signaling and immunity, mitogenic kinase signaling and cell proliferation, as well as cell invasion and metastasis. Acts as an E3 ubiquitin-protein ligase regulating NF-kappa-B signaling and regulates both canonical and non-canonical NF-kappa-B signaling by acting in opposite directions: acts as a positive regulator of the canonical pathway and suppresses constitutive activation of non-canonical NF-kappa-B signaling. The target proteins for its E3 ubiquitin-protein ligase activity include: RIPK1, RIPK2, RIPK3, RIPK4, CASP3, CASP7, CASP8, IKBKE, TRAF1, and BCL10. Acts as an important regulator of innate immune signaling via regulation of Toll-like receptors (TLRs), Nodlike receptors (NLRs) and RIG-I like receptors (RLRs), collectively referred to as pattern recognition receptors (PRRs). Protects cells from spontaneous formation of the ripoptosome, a large multi-protein complex that has the capability to kill cancer cells in a caspase-dependent and caspase-independent manner. Suppresses ripoptosome formation by ubiquitinating RIPK1 and CASP8.
Synonyms: API2; C-IAP2; hIAP-1; hIAP1; MIHC; RNF49; cIAP2; MALT2; AIP1; HAIP1; IAP-1
Tractability: Small molecule: a drug acting on it is in phase 2 or 3 trials; a high-quality ligand is known; it belongs to a druggable protein family. PROTAC: UniProt records ubiquitination sites on it; ubiquitination databases record sites on it; a small molecule that binds it is known.
Target class: Enzyme
Chemical probes: PD006908, PD007284, PD007338, PD007371, PD007564, PD039324, PD039340, PD045879, PD052831, PD053316, PMID25980951-Compound-16
Gene: Protein-coding gene on chromosome 11 (102,317,484 to 102,339,403, forward strand). Ensembl gene ENSG00000023445.
Subcellular location: Cytoplasm; Nucleus
Subcellular location (Human Protein Atlas): Cytosol; Nucleoplasm
Pathways (Reactome):
Immune System: IKK complex recruitment mediated by RIP1; NOD1/2 Signaling Pathway; TICAM1, RIP1-mediated IKK complex recruitment; TNF receptor superfamily (TNFSF) members mediating non-canonical NF-kB pathway; TNFR2 non-canonical NF-kB pathway
Signal Transduction: Regulation of TNFR1 signaling; TNFR1-induced NF-kappa-B signaling pathway; TNFR1-induced proapoptotic signaling
Programmed Cell Death: RIPK1-mediated regulated necrosis; Regulation of necroptotic cell death
Metabolism of proteins: Ub-specific processing proteases
Gene Ontology:
Molecular function: protein binding; transferase activity; ubiquitin-protein transferase activity; cysteine-type endopeptidase inhibitor activity involved in apoptotic process; ubiquitin protein ligase activity; protein-containing complex binding
Biological process: positive regulation of protein ubiquitination; regulation of apoptotic process; regulation of necroptotic process; canonical NF-kappaB signal transduction; cell surface receptor signaling pathway; extrinsic apoptotic signaling pathway via death domain receptors; inflammatory response; intrinsic apoptotic signaling pathway in response to DNA damage; negative regulation of apoptotic process; negative regulation of necroptotic process; non-canonical NF-kappaB signal transduction; positive regulation of canonical NF-kappaB signal transduction; regulation of cell cycle; regulation of inflammatory response; regulation of innate immune response; regulation of nucleotide-binding domain, leucine rich repeat containing receptor signaling pathway; regulation of RIG-I signaling pathway; regulation of toll-like receptor signaling pathway; tumor necrosis factor-mediated signaling pathway; spermatogenesis
Cellular component: cytoplasm; cytosol; nucleoplasm; nucleus; plasma membrane; tumor necrosis factor receptor superfamily complex; protein-containing complex
Genetic constraint (gnomAD): Loss-of-function variants: 20 observed, 53.52 expected, observed/expected ratio (o/e) 0.37, 90% interval 0.26 to 0.54. The upper end of that interval is the gene's LOEUF score, 0.54, which puts it in group 2 of 6, group 1 being the genes least tolerant of losing a copy. Missense variants: 610 observed, 718.54 expected, observed/expected ratio (o/e) 0.85, 90% interval 0.79 to 0.91. Synonymous variants: 229 observed, 253.41 expected, observed/expected ratio (o/e) 0.9, 90% interval 0.81 to 1.01.
Cancer hallmarks: escaping programmed cell death (promotes)
Homologues: Orthologues: chimpanzee BIRC3 (99% identical), macaque BIRC3 (97% identical), guinea pig BIRC3 (85% identical), pig BIRC3 (84% identical), rabbit BIRC3 (83% identical), dog BIRC3 (75% identical), mouse Birc3 (74% identical), rat Birc3 (74% identical), tropical clawed frog birc2 (57% identical), zebrafish birc2 (55% identical), Drosophila melanogaster Diap2 (27% identical), Caenorhabditis elegans bir-2 (12% identical). Paralogues in human: BIRC2 (72% identical), XIAP (32% identical), BIRC6 (27% identical), NAIP (26% identical), BIRC7 (19% identical), NLRC4 (12% identical), BIRC5 (7% identical).
Diseases named in the same sentence as BIRC3 in open-access papers:
BIRC3 is named in the same sentence as 189 diseases in open-access papers, as found by Europe PMC text mining. Sharing a sentence is not in itself a finding about the gene and the disease. The quoted sentences say what the papers report.
breast carcinoma (53 papers, 2004 to 2025). "In breast cancer, BIRC3 upregulation has been associated with enhanced tumor cell survival and doxorubicin resistance." (PMID 40612672, 2025). "BIRC3, an inhibitor of apoptosis protein by inhibiting caspases cascade, serves as a putative biomarker for patients with oesophageal adenocarcinoma and is associated with therapeutic resistance in glioblastoma and breast cancer cells." (PMID 33042828, 2020). "In present study, integrated analysis of scRNA-sequencing data derived from primary breast cancer and bulk RNA-sequencing data from patients receiving ICT identified CXCL13 and BIRC3 as TIL-related markers of ICT sensitivity in breast cancer." (PMID 37488535, 2023). "Based on the expression profiles of marker genes in these two subpopulations, we further developed a CD103+LAG3+ TIL-related prognostic model (CLTRP) based on CXCL13 and BIRC3 genes for predicting the prognosis of breast cancer patients." (PMID 37488535, 2023). "IL-1β induces upregulation of baculoviral IAP repeat containing 3, which is involved in resistance to doxorubicin in breast cancer." (PMID 36264639, 2022). "In this research, one of the genes upregulated in the sentinel or auxillary lymph nodes metastasis compared to the primary breast cancer was BIRC3, together with anti-apoptosis, survival signaling and chemotaxis genes." (PMID 33413657, 2021). "Baculoviral IAP Repeat Containing 3 (BIRC3, also termed cIAP2) is currently believed to be involved in the mechanisms of breast cancer progression." (PMID 34202777, 2021). "BIRC3 results also upregulated by the administration of the inflammatory cytokine 1β (IL-1β) to MCF-7 breast cancer cell line." (PMID 33413657, 2021). "The administration of anti-cancer agents, like the withanidolide Withaferin-A, has been demonstrated to cause the downregulation of XIAP, cIAP2 (BIRC3) and Survivin while inducing apoptosis of human breast cancer cells." (PMID 33413657, 2021). "Much progress has been made in understanding the mechanism of BIRC2 and BIRC3 in multiple cancers, including liver cancer, chronic lymphocytic leukaemia, breast cancer and ovarian cancer." (PMID 33452764, 2021). "In recent studies, BIRC3 was identified as a gene involved in chemoresistance in breast cancer and gliomas." (PMID 32333046, 2020). "The TNF-α pathway controls the expression of BIRC3 and helps protect breast cancer cells against apoptosis." (PMID 32333046, 2020). "We found that the expression of BIRC3 was significantly elevated in breast cancer samples than in normal breast tissues." (PMID 31215169, 2019). "Then we assessed the expression of BIRC3 in human breast cancer tissues by immunohistochemical staining (IHC) in TMA." (PMID 31215169, 2019). "Upregulation of BIRC3 induced by IL-1β results in chemoresistance to doxorubicin in breast cancer cells." (PMID 30630498, 2019). "There were positive correlation between HCP5 and BIRC3 in breast cancer patients (R = 0.625, P < 0.001)." (PMID 31215169, 2019). "The current study detected decreased expression of BIRC3 in breast cancer cells when PADI2 expression was suppressed using anti-PADI2 siRNA." (PMID 27478411, 2016). "It is possible that the increased expression of PADI2 in breast cancer cells up-regulates BIRC3 expression through ER and NF-κB to simulate anti-apoptotic functions." (PMID 27478411, 2016). "In support of this, knockdown of XIAP, a related member of the BIRC-3 anti-apoptotic family in MCF-7 breast cancer cells sensitized these cells to apoptosis mediated by chemotherapeutic drugs." (PMID 21283672, 2011). "Moreover, in breast cancer cells exhibiting high sensitivity to IL-1β, stimulation with IL-1β markedly induces the upregulation of BIRC3 expression, consequently conferring resistance to doxorubicin treatment." (PMID 41035952, 2025). "We detected BIRC3 mRNA and protein level in breast cancer cell lines by qPCR and western blot." (PMID 31215169, 2019).
breast carcinoma (continued). "As described in the Results, we observed upregulation of BIRC-3 mRNA in VDRff cells indicating that breast cancer cells expressing this genotype may be resistant to apoptosis, potentially contributing to an unfavorable prognosis." (PMID 21283672, 2011). "In addition to EGR1, CD63 and BIRC3 were also found to be associated with breast cancer, while USF2′s role in breast cancer has not been clearly investigated." (PMID 34252628, 2021). "Bioinformatics analysis of publicly available data from the TCGA database confirmed statistically significant higher levels of BIRC2 (p = 0.0213), BIRC3 (p = 0.0029), BIRC5 (p = 0.0040) gene expression in breast cancer patients under 51 years of age." (PMID 33673050, 2021). "Activation of IL-1β/IL–1RI/β-catenin signaling pathway was shown to activate EMT in a breast cancer cell model through the formation of a TCF/Lef/β-catenin complex leading to the sequential induction of c-Myc, CCDN1, Snail1, MMP2, and BIRC3 (cIAP2) expression." (PMID 31557902, 2019). "It has been reported that hormone-induced expression of Birc3 and Tnfaip3, target genes of the RANK-TRAF6-mediated canonical NF-κB pathway in normal epithelial cells, in luminal-like breast cancers are involved in cancer cell survival and chemoresistance." (PMID 31396572, 2019). "The results suggested that BIRC3 expression was upregulated in MDA‐MB‐231 and MDA‐MB‐468 than in MCF‐10A and other breast cancer cell lines." (PMID 31215169, 2019). "Real-time PCR verified the increased expression of CA9 and decreased expression of BIRC3 and ACSL4 in the breast cancer cell line." (PMID 27478411, 2016). "We extended our analysis to a breast cancer cell line, MDA-231, and observed that BHLHE41 induced IL-11 up-regulation, and BIRC3 and EDN2 down-regulation." (PMID 27384883, 2016). "As for breast cancer, the function of BIRC3 has not yet been fully characterized." (PMID 36685836, 2022). "Breast cancer is one of the tumor types where BIRC3 has not yet fully characterized." (PMID 33413657, 2021). "Among the eight IAP genes evaluated in this study (BIRC1–8), only cIAP2 (BIRC3) was highly expressed in TNBC cells compared with that in other breast cancer subtypes, while other IAP members were detected in various breast cancer cells, irrespective of their subtypes." (PMID 29108265, 2017).
melanoma (31 papers, 2008 to 2025). A malignant, usually aggressive tumor composed of atypical, neoplastic melanocytes. "ZEB1 binding peaks were also found in other major markers of melanoma cell identity, namely BIRC3, ITGA2 and EGFR, which are up-regulated upon phenotype switching towards the ZEB1high state as confirmed by RT-qPCR." (PMID 38519642, 2024). "Smac mimetics that antagonize BIRC3 activity have also demonstrated activity against melanoma cell lines when combined with TNF-α." (PMID 27074575, 2017). "Nevertheless, despite the upregulation of BCL2A1 and BIRC3 observed in our experiment, the majority of melanoma cells died, suggesting that RGD-apoptins may be able to bypass the defense mechanisms of these tumor cells." (PMID 41465443, 2025). "In this study, the transcript levels of IAP genes including NAIP (BIRC1), BIRC2 (CIAP1), BIRC3 (CIAP2), BIRC5 (Survivin), BIRC6 (Apollon), and XIAP (BIRC4) in UA-treated A-375 melanoma cells were investigated." (PMID 39473730, 2024). "Among them we identify BIRC3, SLIT2, GBP2, and AFAP1 to be involved in the acquisition of BRAFi resistance in melanoma cell lines." (PMID 32708687, 2020). "More recently, Glasheen and colleagues showed that melanoma cells with and without BRAF mutations have elevated levels of the cIAP2 protein (the BIRC3 gene product), which mediates tumor cell resistance to MEK inhibitors." (PMID 41465443, 2025).
ovarian carcinoma (31 papers, 2010 to 2025). A malignant neoplasm originating from the surface ovarian epithelium. "A lower expression level of BIRC3 is associated with a better prognosis for ovarian cancer patients, and BIRC3 knockdown in ovarian cancer cells can recover their sensitivity to cisplatin." (PMID 35754835, 2022). "has reported that an apoptosis-enhancing drug, birinapant, aimed at eliminating the CSC subpopulation in ovarian cancer, re-sensitized ovarian cancer cells to carboplatin via cleavage of caspase 8 and restoration of apoptosis caused by degradation of baculoviral IAP repeat containing 3 (cIAP)." (PMID 31193124, 2019). "Besides, lower expression level of BIRC3 is associated with better prognosis of ovarian cancer patients, and BIRC3 knockdown in ovarian cancer cells can recover their sensitivity to cisplatin." (PMID 30718461, 2019). "Besides, lower expression levels of BIRC3 were associated with a longer survival time of ovarian cancer patients, and BIRC3 knockdown in ovarian cancer cells could recover the cisplatin sensitivity." (PMID 30718461, 2019). "BIRC3, a E3 ubiquitin-protein ligase that regulates NFkB activation and anti-apoptotic caspase regulation can be induced by IL-6 treatment in ovarian cancer cells." (PMID 39131380, 2024). "CRL4 has been proved to play an important role in apoptosis and drug resistance by targeting baculoviral IAP repeat containing 3 (BIRC3) in ovarian cancer cells." (PMID 32762026, 2020). "It is intriguing to reveal the regulatory mechanism of BIRC3 in chemotherapy-resistant ovarian cancer." (PMID 30718461, 2019). "Next, to validate this finding in an independent dataset, we investigated the effect of BIRC3 expression using public ovarian cancer dataset with 294 unique ovarian cancer samples." (PMID 30718461, 2019). "To further explore the role of BIRC3 in cistplatin resistance of ovarian cancer, we first examined the levels of BIRC3 in ovarian cancer and normal interstitial tissues." (PMID 30718461, 2019). "CDC25A was significantly overexpressed (p=0.02) and BIRC3 was significantly down-regulated (p=0.02) after SMYD3 knockdown in ovarian cancer PDX model." (PMID 31417652, 2019). "We found that BIRC3 expression correlated inversely with ovarian cancer patient outcome, while BIRC2, BIRC4, BIRC5, and BIRC7 had no significant impact on patient outcome." (PMID 30718461, 2019). "Collectively, all these data indicate that BIRC3 is another key functional target of CRL4, and both CRL4 and BIRC3 serve as crucial terminators of ovarian cancer chemoresistance." (PMID 30718461, 2019). "As we expected, CRL4 knockdown blocked STAT3 signaling activation and reduced BIRC3 expression in ovarian cancer cells, strongly suggesting that the upregulation of BIRC3 by CRL4 was also mediated by STAT3 signaling pathway in ovarian cancer." (PMID 30718461, 2019). "The result showed that the positive expression rate of BIRC3 in ovarian cancer tissue (92.96%, 66/71 cases) was higher than that in normal interstitial tissue (26.7%, 4/15 cases), indicating that BIRC3 was overexpressed in ovarian cancer tissue." (PMID 30718461, 2019). "Additionally, our current findings of CRL4 regulation on the expression of antiapoptotic protein BIRC3 in ovarian cancer support the notion that abnormal expression of CRL4 is mostly responsible for chemoresistance in ovarian cancer." (PMID 30718461, 2019). "Moreover, BIRC3 downregulation in CRL4-knockdown cells correlated with increased apoptosis in response to cisplatin, and ovarian cancer patients with lower BIRC3 expression had better prognosis." (PMID 30718461, 2019). "Moreover, BIRC3 has been reported as a novel inducer of platinum resistance in ovarian carcinoma cells." (PMID 28114404, 2017). "Hence, CRL4 appears to be a crucial point of BIRC3 regulation in ovarian cancer resistance." (PMID 30718461, 2019).